CTLA4 (cytotoxic T-lymphocyte associated protein 4)
Diseases named in the same sentence as CTLA4 in open-access papers (continued):
Sharing a sentence is not in itself a finding about the gene and the disease.
melanoma (continued). "We have shown that human melanomas that express CTLA4 and other interferon-γ response genes had significant durable responses to anti-CTLA4 immunotherapy, ipilimumab." (PMID 29762513, 2018). "Radiolabeled IgG 8C3 showed significant therapeutic efficacy in murine melanoma, safety towards healthy melanin-containing tissues and favorable comparison with the anti-CTLA4 antibody." (PMID 29615812, 2018). "On the same line, genetic defects in the IFN-γ pathway have been shown to reduce the chance of response to antibodies targeting CTLA-4 in melanoma patients." (PMID 29482595, 2018). "Inhibition of the ICRs with anti-PD-1 and anti-CTLA-4 antibodies enables T-cell-mediated killing of melanoma cells and significantly improved patient outcomes in recent years." (PMID 29875777, 2018). "The therapeutic efficacy of 213Bi- and 188Re-labeled 8C3 and its comparison with anti-CTLA4 immunotherapy was performed in B16-F10 murine melanoma model." (PMID 29615812, 2018). "We have recently obtained promising results in early-stage melanoma patients receiving a single low dose of the anti-CTLA4 checkpoint inhibitor tremelimumab." (PMID 30208866, 2018). "In this study, we analyzed pre-treatment peripheral blood mononuclear cell (PBMC) samples from melanoma patients receiving anti-CTLA-4 or anti-PD-1, to investigate potential correlations in baseline immune features and clinical outcomes." (PMID 29510697, 2018). "Several immune populations have been assessed and correlated with the response to ipilimumab, a CTLA-4 blocking antibody, in melanoma patients." (PMID 29495308, 2018). "Phase III data have shown that combination CTLA-4 and PD-1 inhibition improves progression-free survival within melanoma establishing a new standard of care." (PMID 30110927, 2018). "The evidence of increased (≥1000/μL) absolute lymphocyte count (ALC) upon infusion of an immune checkpoint agent represented the first observation of clinical benefit in melanoma patients with advanced disease treated with anti-CTLA-4 mAb." (PMID 30004433, 2018). "After both PDXs and melanoma cell xenografts reached ~ 150–200 mm3, animals were treated with humanized anti-PD-1 antibody or anti-CTLA-4 and evaluated for tumor growth, survival, and potential mechanism of action." (PMID 30185216, 2018). "CTLA-4 was the first immune checkpoint that was targeted to enhance T cell responses in patients suffering from melanoma." (PMID 30233564, 2018). "Of note, PD-1 blockage (e.g., nivolumab) shows milder autoimmunity-related side effects than anti-CTLA-4 treatment (e.g., ipilimumab) in melanoma patients." (PMID 30158932, 2018). "In this study, we discovered that a higher frequency of memory T cells in baseline PBMC is a potential biomarker candidate to predict clinical response to anti-CTLA-4 treatment in advanced melanoma patients." (PMID 29510697, 2018). "Severity and site of toxicity (gastrointestinal (GI), endocrine, skin and/or other) and treatment termination status for baseline sera samples from anti-CTLA-4 (n = 39), anti-PD-1 (n = 28), and combination (n = 11) melanoma patients." (PMID 29606147, 2018). "Consistent with this, we also showed in the limited post-treatment cohorts with gene expression data, that melanomas responding to ICB (particularly anti-CTLA4) display a gene expression signature derived from our hot cluster." (PMID 30104673, 2018). "Pseudoprogression was first described in three patients with metastatic, unresectable melanoma treated with ipilimumab, a human anti-CTLA-4 monoclonal antibody." (PMID 29549485, 2018). "Despite the remarkable success of ICBs in improving objective response rates in a subset of patients, it has been demonstrated that only ≤ 20–30% of tumor patients with NSCLC, RCC, and melanoma benefited from CTLA-4 or PD-1 blockade." (PMID 30135516, 2018). "The authors diagnosed a small vessel vasculitis following treatment with anti-CTLA-4 (ipilimumab) for a resected stage III B/C melanoma." (PMID 30446009, 2018).
melanoma (continued). "Recently, the role of soluble NKG2DLs as candidate predictive biomarkers of clinical outcome to immunotherapy has been confirmed in a cohort of N = 194 melanoma patients treated with anti-CTLA-4 or anti-PD-1 mAb monotherapy or their combinations." (PMID 30004433, 2018). "Of note regarding the immunotherapy studies, the expression of checkpoint molecules, including CTLA-4 and PD-1, has been observed on peripheral blood lymphocytes of several canine patients affected by mastocytoma, melanoma, and renal cell carcinoma." (PMID 29534457, 2018). "In an experiment on murine preclinical models, vaccination with B16-Flt-3 ligand (Fvax) along with the use of CTLA-4 antibody promoted tumor rejection in 10% of mice with pre-implanted B16-BL6 melanoma." (PMID 29769148, 2018). "Ipilimumab was firstly approved for advanced melanoma in 2011, which symbolizes the remarkable clinical success of anti-CTLA-4 and thus elicits further investigations into PD-1/PD-L1 pathway." (PMID 30294272, 2018). "The IT delivery of IL-2 together with the checkpoint inhibitor anti-CTLA-4, delivered either systemically or locally, represents a promising approach in melanoma patients (NCT01480323, NCT01672450)." (PMID 30619273, 2018). "In another study, Wang and colleagues observed an upregulation of Ki67, ICOS, and GATA3 in blood CD4+ and CD8+ T cells of anti-CTLA-4 antibody-treated melanoma patients." (PMID 29494517, 2018). "The percentage of CTLA-4 expressing cells CD4+ T cells was similar in melanoma patients and controls, both in young subjects and old subjects." (PMID 29546435, 2018). "The use of anti-CTLA-4 in addition to anti-PD-1 antibodies resulted in increased overall survival rates in previously untreated melanoma patients." (PMID 29875199, 2018). "The impact of preventing interference by CTLA-4 has been demonstrated in melanoma patients where CTLA-4-blockade induced a broadening of tumor directed T cell responses." (PMID 29032503, 2018). "Enhancer of zeste homolog 2 blockade led to reduced PD-L1 mRNA levels and a decrease in PD-L1+ Pax3+ in melanoma cells, which was maintained during concomitant IL-2cx or anti-CTLA-4 immunotherapy." (PMID 29843754, 2018). "CTLA-4 monoclonal antibodies such as ipilimumab (Yervoy) and tremelimumab block B7-interaction and have been used to treat melanoma." (PMID 29701673, 2018). "Immune checkpoint inhibitors (anti-CTLA-4, anti-PD-1, or the combination) enhance anti-tumor immune responses, yielding durable clinical benefit in several cancer types, including melanoma." (PMID 29606147, 2018). "Consistent with this preclinical evidence, clinical benefit has been observed with ipilimumab, a human IgG1 anti-CTLA-4 antibody, in patients with advanced stages of melanoma." (PMID 29617360, 2018). "Systemic immunity elicited by CTLA-4 blockade has been previously shown to promote anti-tumor immunity against melanoma metastases within the central nervous system, indicating that CTLA-4 blockade functions outside of the CNS." (PMID 29891009, 2018). "Encouraging results from combination treatment with PD-1 and CTLA-4 inhibitors have been observed in melanoma and NSCLC." (PMID 29545941, 2018). "The anti-CTLA-4 antibody Ipilimumab was first shown to be effective in patients against advanced melanoma." (PMID 29570634, 2018). "Treatment with anti-CTLA-4 benefits approximately 20% of patients with advanced melanoma, and a small proportion of these patients remain disease free 10 years after treatment." (PMID 29968076, 2018). "In melanoma patients who have progressed on anti-CTLA-4 therapy and subsequently treated with anti-PD-1 (n = 35), an increase in the number of unique CDR3 sequences (richness) was associated with clinical benefit." (PMID 29968076, 2018). "Both the Food and Drug Administration (FDA) and the European Medicinal Agency (EMA) approved the combination of CTLA-4 and PD-1 blockade for advanced melanoma." (PMID 30004433, 2018).
melanoma (continued). "Checkpoint blockade using anti CTLA-4 and anti PD-1 is effective in “hot” tumors like melanoma with pre-existing immune infiltrates; however, “cold” tumors like prostate cancer respond poorly." (PMID 30400822, 2018). "They analyzed tumor samples from melanoma patients treated sequentially with anti-CTLA-4 and anti-PD-1 via WES and TCR sequencing." (PMID 29896449, 2018). "Antibodies that block the immune checkpoint receptors PD1 and CTLA4 have revolutionized the treatment of melanoma and several other cancers, but in the process, a new class of drug side effect has emerged—immune related adverse events." (PMID 30349540, 2018). "Immunotherapeutic strategies targeting CTLA-4 or the PD-1/PD-L1 axis induce objective clinical responses and improve survival in patients with various tumor types, including melanoma, NSCLC, and RCC." (PMID 29494517, 2018). "Immunotherapies, including checkpoint inhibitors (CIs) such as cytotoxic T-lymphocyte antigen-4 (CTLA-4) and programmed death-1 (PD-1) inhibitors, are revolutionizing the treatment of advanced melanoma." (PMID 30190927, 2018). "The IT injection of Newcastle disease virus combined with systemic injection of an anti-CTLA-4 antibody resulted in slower tumor growth, prolonged survival and protected the mice from a subsequent tumor rechallenge in a melanoma setting." (PMID 30619273, 2018). "In this review, we summarize the current landscape of combination therapy with anti-PD-1/PD-L1 plus anti-CTLA-4 MoAbs for patients with melanoma and non-small cell lung cancer (NSCLC)." (PMID 29769148, 2018). "Of interest, in melanoma, the activity of anti-CTLA-4 antibodies is also attributed to the selective depletion of Tregs mediated by Fc receptors." (PMID 30250471, 2018). "The blocking of CTLA-4 reduces tumor growth in murine models, including melanoma, and colon carcinoma." (PMID 29988281, 2018). "Melanoma patients (pts) who received anti-CTLA-4 (ipilimumab), anti-PD-1 (pembrolizumab or nivolumab), or the combination at the Center for Immuno-Oncology and Melanoma at DFCI in the past 5 years (up to December 31- 2016) were included." (PMID 30400822, 2018). "Compared to controls, both PFS and OS resulted significantly improved by treatment with ICIs in both genders, but men showed lower HR than women, particularly when treated with anti-CTLA-4 in advanced melanoma." (PMID 30545122, 2018). "This implicates a role for targeting CTLA4 on melanoma cells in mediating the effects of anti-CTLA4 immunotherapy." (PMID 29762513, 2018). "Blockade of cytotoxic T-lymphocyte antigen-4 (CTLA-4) with ipilimumab showed the first evidence of improved survival in advanced melanoma and long-term survival can be achieved." (PMID 29610684, 2018). "The combination of anti-CTLA-4 with T-VEC has been investigated in a Phase Ib clinical trial for the treatment of advanced melanoma where the intratumoral doses of T-VEC are followed by intravenous ipilimumab administration." (PMID 29857493, 2018). "Targeting CTLA-4 with a human anti-CTLA-4 antibody has demonstrated therapeutic success in the treatment of melanoma." (PMID 29707526, 2018). "Monocloncal antibodies targeting CTLA-4 and PD-1/PD-L1 have been approved for use in the clinic for non-small cell lung cancer, renal cell carcinoma, melanoma, Merkel's cell carcinoma, Hodgkin lymphoma and various other malignancies." (PMID 30186768, 2018). "In an innovative study, Lorger’s group described the role of combinative anti-PD-1/anti-CTLA-4 therapy in a mouse model of melanoma brain metastasis." (PMID 30483064, 2018). "More recently, it has been reported that anti-CTLA-4 therapy induces the expansion of melanoma-infiltrating ICOS+ TH1-like CD4+ T cells as well as exhausted-like CD8+ T cells." (PMID 29494517, 2018). "Treatment of patients with unresectable or stage IV melanoma with the CTLA-4 inhibitor ipilimumab conferred overall survival benefit leading to Food and Drug Administration (FDA) approval in 2011." (PMID 30227886, 2018).
melanoma (continued). "CyTOF-based immune profiling of peripheral blood samples collected from anti-CTLA-4 and anti-PD-1-treated melanoma patients showed a distinct set of biomarkers in response to therapy." (PMID 30546008, 2018). "In preclinical trials combination of PD-1 and CTLA-4 therapies was shown to have a synergistic effect on B16 melanoma tumour growth." (PMID 29570634, 2018). "Antibodies targeting CTLA4 induce durable responses in some patients with melanoma and are being tested in a variety of human cancers." (PMID 30400822, 2018). "The combination of PD-1 and CTLA-4 blockade has demonstrated higher response rates in advanced melanoma, while combination with LAG3 blockade are still carrying on clinical trials (NCT03250832, NCT02658981, NCT01968109, NCT03005782)." (PMID 30607140, 2018). "Early trial results on the combination of PD-L1 and CTLA-4 targeting were first found to be valuable in malignant melanoma." (PMID 30057891, 2018). "Activating the immune response by anti-CTLA4 or PD1 blockade for melanoma treatment also induces changes in metabolic uptake in immune organs like lymph nodes or spleen." (PMID 30112704, 2018). "The response was significant in different tumors, including melanoma, with better clinical benefit and minor toxicity compared to anti-CTLA-4 therapy." (PMID 29371600, 2018). "PD-1 and CTLA-4 combination blockade expands infiltrating T cells and reduces regulatory T and myeloid cells within B16 melanoma tumors." (PMID 30400822, 2018). "The synergistic blocking of PD-1 and CTLA-4 enhances and prolongs the efficacy of cancer vaccine to reject B16 melanoma cells by elevating the CD8+ / Treg ratio." (PMID 29988281, 2018). "This perspective aligns with the clinical success of concomitant administration of anti-PD-1 and CTLA-4 antibodies in melanoma and lung cancer patients versus monotherapy." (PMID 29617360, 2018). "IFN-γ signaling activates expression of CTLA-4 in melanoma cells, and after ipilimumab (anti-CTLA-4) treatment, human melanomas upregulated IFN-γ responsive genes, including CTLA-4, which associated with durable response." (PMID 30108594, 2018). "Our findings suggest that response to anti-CTLA-4 and anti-PD-1 in advanced melanoma patients is complex and multifaceted." (PMID 29510697, 2018). "The therapeutic potential of CTLA-4 antibody blockade was first demonstrated in murine cancer models of melanoma, mammary and prostate cancer." (PMID 30319637, 2018). "In contrast, the tumor grew progressively in mice treated with anti-CTLA-4 or anti-4-1BB mAb monotherapy in this challenging B16 melanoma model." (PMID 29348598, 2018). "Anti-CTLA-4 therapy (Ipilimumab) was shown to induce cancer regression in metastatic kidney cancer and melanoma." (PMID 29515971, 2018). "An obvious first way to address these problems is by taking advantage of ICBs, such as anti-PD-1, anti-PD-L1, anti-CTLA-4, and others in development, which have been successful in a significant fraction of patients with melanoma or lung cancer." (PMID 29482595, 2018). "Particularly relevant was the improvement in term of PFS and OS associated with pembrolizumab (Keytruda®), a second anti-PD-1 antibody utilized for treatment of advanced melanoma compared to anti-CTLA-4 therapy." (PMID 29371600, 2018). "This synergy of anti-CTLA-4 or anti-PD-L1 with a range of RT doses and fractionations has been demonstrated in immune-competent mouse models of lung, breast, melanoma, and colorectal cancers." (PMID 30360504, 2018). "Melanoma has served as the test bed for ICI with the initial development of anti-CTLA-4 antibodies (ipilimumab) and more recently antibodies that inhibit the programmed death-1 axis (e.g., nivolumab, pembrolizumab)." (PMID 29445373, 2018). "Some of the findings in this study are partly validated by another study published recently which showed that memory subsets were predictive of response to CTLA-4 blockade in melanoma patients." (PMID 29510697, 2018).
melanoma (continued). "In light of initial success in patients with melanoma, efforts to explore the indications for combination checkpoint inhibition with anti-PD-1/PD-L1 and anti-CTLA-4 MoAbs have diversified to a large number of tumor histologies." (PMID 29769148, 2018). "On a related note, it has been previously shown that CTLA-4 blockade in melanoma patients can broaden the repertoire of tumor-specific CD8+ T cells compared to the pre-existing viral-specific T cell repertoire detected at the start of therapy." (PMID 29617360, 2018). "A cocktail of the broad-spectrum antibiotics ampicillin, colistin, and streptomycin, as well as the beta-lactam imipenem alone, were found to compromise the anticancer effect of the anti-CTLA-4 therapy in mouse models of sarcoma, melanoma, and colon cancer." (PMID 29789015, 2018). "Combined therapy with anti-PD-1/PD-L1 and anti-CTLA-4 MoAbs in advanced melanoma has exhibited better survival outcomes in comparison with single-agent immunotherapy." (PMID 29769148, 2018). "Long-term survival data for patients with melanoma treated with ipilimumab (anti-CTLA-4) indicates 20% of patients show evidence of continued durable disease control or response 5-10 years after starting therapy." (PMID 29319049, 2018). "The introduction of the anti-CTLA-4 Ipilimumab in 2011, followed by the two anti-PD-1 inhibitors, Nivolumab and Pembrolizumab in 2015 for melanoma patients’ management has been revolutionary in the immune-oncology field." (PMID 29534457, 2018). "On the other hand, poly(lactide-co-glycolide) vaccines combined with anti-CTLA-4 checkpoint inhibitors demonstrated promising results, regressing B16 melanoma tumors in mice and increasing survival rates by 75%." (PMID 30191140, 2018). "Combination treatments with CTLA4 and PD-1 blockers have been approved as the first line therapy for advanced melanoma patients and are being tested in other tumor types with different dose levels and intervals of anti-CTLA4 to reduce toxicity." (PMID 29482595, 2018). "The blockade of the VEGF receptor by axitinib in combination with anti-CTLA-4 antibodies increased survival of mice with subcutaneous melanoma and intracranial melanoma metastasis." (PMID 29942309, 2018). "Pretreatment sPD-L1 levels reportedly correlate with progression of advanced melanoma treated with anti-CTLA-4 or anti-PD-1 antibody." (PMID 30073150, 2018). "In this context, anti-CTLA-4 and anti-PD-1 monoclonal antibodies have demonstrated survival benefits in numerous cancers, including melanoma and non-small-cell lung carcinoma." (PMID 29403496, 2018). "In particular for metastatic melanoma and metastatic renal cell carcinoma (RCC), ICI compare favorably in terms of response rates (approximate ORR on anti-PD-1 mAb in RCC: 25%; in melanoma: 40 and 58% when combined with anti-CTLA-4 mAb)." (PMID 30327656, 2018). "Treatment of unresectable or stage IV melanoma patients who received prior chemotherapy with the investigational CTLA-4 inhibitor tremelimumab as part of a phase II study demonstrated a 6.6% objective response rate." (PMID 30227886, 2018). "The combination of PD-1 and CTLA-4 blockers results in greater anti-tumor effect than monotherapy regimens in melanoma, and is currently being evaluated in NSCLC5–8." (PMID 30097571, 2018). "For instance, patients with advanced melanoma refractory to treatment with ipilimumab, which is targeting CTLA-4, showed good clinical response to anti-PD-1 therapy." (PMID 30105035, 2018). "Mice and melanoma patients immunized or populated with Bacteriodes fragilis respond better to treatment with Ipilimumab, a monoclonal antibody against CTLA-4." (PMID 29701673, 2018). "Anti-MARCO treatment potently repolarised TAMs in an FcγRIIb-dependent manner and in combination with anti-CTLA4 immunotherapy showed enhanced anti-tumour effects in mouse models of melanoma and colon carcinoma." (PMID 30577495, 2018).